MIR320C2 (microRNA 320c-2)
Synonyms: hsa-mir-320c-2; formerly MIRN320C2
Gene: MicroRNA gene on chromosome 18 (24,321,686 to 24,321,735, forward strand). Ensembl gene ENSG00000212051.
Gene Ontology:
Biological process: cellular response to glucose stimulus; long-term synaptic potentiation; miRNA-mediated post-transcriptional gene silencing; negative regulation of gene expression; positive regulation of stem cell proliferation
Cellular component: RISC complex
Homologues: Orthologues: chimpanzee ptr-mir-320c-2 (100% identical), tropical clawed frog xtr-mir-320 (50% identical). Paralogues in human: MIR320A (88% identical), MIR320E (88% identical), MIR320B1 (86% identical), MIR320B2 (86% identical), MIR320D2 (80% identical).